RN7SL472P (RNA, 7SL, cytoplasmic 472, pseudogene)
Gene: Miscellaneous RNA gene on chromosome 14 (102,077,180 to 102,077,472, reverse strand). Ensembl gene ENSG00000240457.
Homologues: Orthologues: chimpanzee Metazoa_SRP (99% identical). Paralogues in human: RN7SL2 (83% identical), RN7SL1 (83% identical), RN7SL3 (82% identical), RN7SL769P (81% identical), RN7SL664P (81% identical), RN7SL559P (80% identical), RN7SL743P (80% identical), RN7SL126P (79% identical), RN7SL113P (79% identical), RN7SL45P (79% identical), RN7SL678P (79% identical), RN7SL679P (79% identical), and 705 more.